BTK (Bruton tyrosine kinase)
Diseases named in the same sentence as BTK in open-access papers (continued):
Sharing a sentence is not in itself a finding about the gene and the disease.
lymphoma (continued). "On the contrary, other BTK inhibitors, such as AVL-292, are in clinical trials for different hematological malignancies such as several B-cell leukemias/lymphomas, myelomas and acute myelogenous leukemia, and autoimmune diseases." (PMID 31200752, 2019). "The validity of this concept has first been demonstrated by the therapeutic efficacy of the BTK inhibitor ibrutinib in ABC DLBCL and other lymphoid cancers relying on chronic BCR signaling." (PMID 29587428, 2018). "Bruton tyrosine kinase (BTK) is a critical effector molecule for B cell development and plays a major role in lymphoma genesis." (PMID 27590878, 2016). "First, we demonstrated that acalabrutinib potently inhibited BTK activity and downstream effectors in CLBL1, a canine B-cell lymphoma cell line, and primary canine lymphoma cells." (PMID 27434128, 2016). "LFM-A13 is a novel, first-in-class, dual BTK/Polo-like kinases (PLK) inhibitor with anti-proliferative, pro-apoptotic, and chemosensitising effects in leukemia/lymphoma and breast cancer cells." (PMID 23958373, 2013). "The aim was to determine the effect of the Bruton tyrosine kinase (Btk)-selective inhibitor PCI-32765, currently in Phase I/II studies in lymphoma trials, in arthritis and immune-complex (IC) based animal models and describe the underlying cellular mechanisms." (PMID 21752263, 2011). "These combined findings strongly suggest that the inhibition of cell metabolism is an important, if not critical, mechanism responsible for the efficacy of BTK inhibitors as therapeutic agents in lymphoma." (PMID 38965536, 2024). "Despite initial success with treating ibrutinib-resistant lymphomas with non-covalent BTK inhibitors, soon thereafter, studies demonstrated patients experiencing resistance to this new line of therapeutics." (PMID 39062757, 2024). "While the existence of this mechanism of resistance to BTK inhibition remains to be confirmed in lymphoma patients, monitoring ROR1 expression may become an important component of managing lymphomas treated with a BTK inhibitor." (PMID 38638855, 2024). "Patients with lymphoma receiving BTK inhibitors, undergoing active therapy, and lacking disease remission exhibited a higher risk for pneumonia associated with COVID-19." (PMID 39834945, 2024). "Unregulated BCR signaling, on the other hand, contributes to the development and persistence of B cell-derived cancers, as evidenced by the effectiveness of inhibitors targeting the proximal signaling proteins Bruton tyrosine kinase (BTK) and PI3K in B-cell leukemias and lymphomas." (PMID 39108267, 2024). "Approximately half of patients with lymphoma struggle to produce effective SARS-CoV-2 antibodies, particularly those undergoing B cell depletion therapies such as anti-CD20 monoclonal antibodies and Bruton's tyrosine kinase (BTK) inhibitor." (PMID 39140001, 2024). "More importantly, it can also inhibit the growth of lymphoma and leukemia cells, overcoming the limitations of the BTK inhibitor, ibrutinib, in the treatment of non-mutant MyD88 lymphoma and providing new treatment ideas for WT MyD88 lymphoma." (PMID 38785969, 2024). "In summary, in human lymphoma cells LUX and IB have quite distinct mechanistic effects on the phosphorylation of BTK and its activity, and on the upstream kinases SYK and LYN, and the adaptor protein BLNK against which LUX is very potent and IB had little effect." (PMID 36888611, 2023). "Currently, several small molecule inhibitors of BTK, such as ibrutinib, acalabrutinib, and zanubrutinib, have been approved for the treatment of certain types of lymphoma that have relapsed and/or have not responded to other therapies." (PMID 37929016, 2023).
lymphoma (continued). "Similar to BTK inhibitors like ibrutinib, therapeutic inhibitors against additional targets in the antigen/BCR-integrin axis may provide great clinical efficacy in lymphoma and leukemia patients." (PMID 35440579, 2022). "In addition to the primary indication of BTK inhibitors in CLL and lymphomas, their efficacy has recently been demonstrated in AML and solid tumours." (PMID 36297430, 2022). "Treatment with B-cell directed therapies, such as anti-CD20 monoclonal antibodies and Bruton’s tyrosine kinase (BTK) inhibitors, further compromises the ability of patients with lymphoma to mount an antibody response following vaccination and persists over time." (PMID 36454941, 2022). "Inhibiting BTK has yielded remarkable gains for patients with B-cell malignancies, and the development of pirtobrutinib furthers these gains by introducing a new treatment option for patients with CLL/SLL, MCL, and other lymphomas." (PMID 35747462, 2022). "A key feature of BTK is its interaction with the PI3K/Akt signaling pathway and function as the upstream of NF-kB and ERK, thereby affecting the proliferation, survival, and differentiation of lymphoma cells." (PMID 34315851, 2021). "FLI1 also positively regulated genes that are downregulated in lymphoma cell lines exposed to signaling inhibitors such as the PI3K delta inhibitor idelalisib, the BTK inhibitor ibrutinib and the BET Bromodomain inhibitors, while negatively controlling genes upregulated by the same compounds." (PMID 34763718, 2021). "Both BTK and PI3K pathways are activated by the B cell receptor in CLL, and co-inhibition of BTK and PI3K delta (idelalisib) in preclinical model of aggressive lymphomas is reported to significantly improve the efficacy." (PMID 34439194, 2021). "MCL cells can develop de novo resistance through a dynamic interplay between lymphoma cells and their TME, mediated by the triggering of BTK, ERK, and AKT activation and enhanced survival through the synthesis of several chemokines and cytokines, including BAFF." (PMID 32545704, 2020). "Overall, BTK inhibition by Ibrutinib monotherapy seems to be able to control progression but is not not sufficient to fully eradicate many lymphomas." (PMID 26540570, 2015). "It will be interesting to unravel whether MALT1 may be active in other Ibrutinib sensitive lymphomas such as CLL or MCL and to determine whether combinatorial BTK and MALT1 inhibition may potentially hold benefits for lymphoma patients beyond ABC DLBCL." (PMID 26540570, 2015). "BTK and PLCγ are functionally connected, as knockdown of BTK resulted in reduced PLCγ phosphorylation in response to stimulation of the TREM-1/DAP12 pathway in a lymphoma cell line." (PMID 23825946, 2013). "Pirtobrutinib, the only approved third-generation noncovalent BTK inhibitor, is used to treat R/R lymphomas after at least two lines of prior systemic therapy, and the effectiveness and efficacy of noncovalent BTK inhibitors in treating PCNSL remain unknown." (PMID 39777345, 2024). "Although non-covalent and covalent BTKis have been found to target BTK selectively, these inhibitors may not mitigate BTK-independent BTKi resistance mechanisms found in lymphoma." (PMID 37626420, 2023). "This preclinical study demonstrated differential binding of pirtobrutinib to both BTK and BTKC481 substitution mutants that prevented BTKY551 phosphorylation in the activation loop and inhibited BTK signaling in multiple B cell lymphoma cell lines and lymphoma xenograft tumor growth." (PMID 37626420, 2023). "Thus, in BCR-activated lymphoma cells, phosphorylation of BTK at Y551 is not a prerequisite for autophosphorylation at Y223, or else Y223 is being phosphorylated by some other kinase." (PMID 36888611, 2023).
lymphoma (continued). "Furthermore, silencing of CYLD expression rendered BCR-dependent lymphoma cell lines less sensitive to inhibition of NF-κΒ signaling and cell proliferation by BCR pathway inhibitors, e.g., the BTK inhibitor ibrutinib, indicating that these effects are partially mediated by CYLD." (PMID 36922488, 2023). "Thus, we investigated if ASK120067 could inhibit BTK and ITK directly, and the potential therapeutic effects of ASK120067 against lymphoma and leukemia." (PMID 36588692, 2022). "Interestingly, BTK inhibition can indirectly downregulate PD-L1 signaling in DLBCL cells, and enhance the anti-tumour therapeutic effects of PD-1 blockade in mouse models of lymphoma, which might be proven synergistic with anti-PD-1 immunotherapy (NCT02362035)." (PMID 34572910, 2021). "Our study indicated that there was no significant change in NFκB activity in both lymphoma cell lines with CYLD knockout (OCI-Ly10 and HBL-1) after BTK inhibitor treatment, suggesting that BTKis down-regulated NFκB activity is dependent on the CYLD pathway." (PMID 33827598, 2021). "However, databases contain partly overlapping information on only selected protein sets, as discussed in a recent review, and in the case of BTK may contain conflicting information from studies more relevant to the field of oncology rather than immunology as BTK is a target for lymphoma treatment." (PMID 30958864, 2019).
B-cell lymphomas (108 papers, 2012 to 2025). "Zanubrutinib is a BTK inhibitor reported to be effective for B‐cell lymphomas with MYD88 and CD79b mutations, double expression of MYC and BCL2/BCL6, and CD5 expression." (PMID 39054569, 2024). "Bruton’s tyrosine kinase (BTK) has been implicated in the pathogenesis of B-cell lymphomas through its role in the B-cell receptor (BCR) signaling cascade, providing a strong rationale for its inhibition as a therapeutic strategy." (PMID 39796724, 2024). "B-cell lymphomas that harbor the MYD88L265P mutation form a complex with phosphorylated Bruton’s tyrosine kinase (BTK) and are responsive to BTK inhibition." (PMID 37954584, 2023). "The Bruton tyrosine kinase inhibitor ibrutinib, given alone or in association with other molecules, has proven effective in numerous B-cell lymphomas." (PMID 35406532, 2022). "Bruton’s tyrosine kinase (BTK) is a mediator of B-cell receptor pathway activation associated with nuclear factor-κB pathway activation in diverse B-cell lymphomas." (PMID 31076643, 2019). "We next sought genetic evidence for a regulatory role of BTK in nuclear localization of native IK in lymphoid cells using BTK-deficient DT40 chicken B-cell lymphoma clones that were established by homologous recombination knockout." (PMID 23977012, 2013). "In addition to variants that were common among non-neoplastic control samples, 25 potentially high-impact variants, predicted by the Ensembl Variant Effect Predictor, were found to affect PI3K and BTK only in lymphoid cell lines and primary B-cell lymphomas." (PMID 34884478, 2021). "Therefore, ibrutinib as a BTK inhibitor may be used as a prophylactic or therapeutic agent for canine pyometra caused by B cell lymphoma." (PMID 37101686, 2023). "For example, patients with A20-mutant B-cell lymphomas exhibit differential responses to certain therapies, such as Bruton’s tyrosine kinase (BTK) inhibitors." (PMID 40214497, 2025). "The introduction of BTK inhibitors has revolutionized the treatment landscape of B-cell lymphomas by disrupting the pathological mechanisms in malignant B cells, leading to improved drug response and reduced toxicity." (PMID 40235547, 2025). "BTK is primarily involved in the B-cell receptor/NF-κB signaling pathway, and BTK inhibitors have emerged as promising drugs for B-cell lymphoma." (PMID 40842532, 2025). "Tirabrutinib is a potent, irreversible, and highly selective Bruton’s tyrosine kinase (BTK) inhibitor that has demonstrated significant therapeutic activity in patients with relapsed or refractory B-cell lymphoma." (PMID 40235547, 2025). "Targeting the BCR pathway has emerged as a promising therapeutic strategy for B-cell lymphomas, with BTK inhibitors at the forefront of this approach." (PMID 40235547, 2025). "Since BTK played a key role in the survival of B-cell malignancies, PROTACs targeting BTK were considered a potential treatment strategy for B-cell lymphomas." (PMID 41226551, 2025). "Ibrutinib is an FDA-approved B-cell lymphoma/lymphocytic leukemia agent that inhibits BTK (Bruton tyrosine kinase) activation, leading to decreased B-cell receptor signaling and decreased proliferative potential." (PMID 38589905, 2024). "Targeted degradation of BTK, a crucial target in R/R B-cell lymphomas, by PROTACs, has been explored in three completed clinical trials, which were presented at the American Society of Hematology Meeting in 2023." (PMID 39518937, 2024). "BTK inhibitors are a kind of small molecule targeting the critical component BTK on the signal pathway of B Cells, related to B cell proliferation and survival, making it a significant therapeutic target for B-cell lymphoma." (PMID 39131702, 2024). "The application of ibrutinib, the first-generation small-molecule BTK inhibitor and other, even more specific BTK inhibitors has significantly changed the treatment landscape for various B-cell lymphomas, including MCL." (PMID 39161974, 2024).
B-cell lymphomas (continued). "Potential synergism between BTK inhibitor and lenalidomide in treating aggressive B-cell lymphoma has been suggested." (PMID 38555311, 2024). "The Bruton tyrosine kinase (BTK) inhibitor Acalabrutinib has shown some activity in refractory B-cell lymphoma but with limited durable response and a phase 1 trial is currently evaluating combination with AZD9150 as part of the PRISM study." (PMID 38339245, 2024). "Novel therapies such as CAR-T, BTK inhibitors and PD-1 inhibitors have changed the management of aggressive B-cell lymphomas." (PMID 39513887, 2024). "Research on BTK has been gaining momentum since the approval of BTK-targeted inhibitors as a first-line treatment for B-cell lymphomas." (PMID 39518937, 2024). "BTK inhibitors have gained considerable attention in recent years due to their demonstrated efficacy in treating B-cell lymphoma." (PMID 39131702, 2024). "Persistent IRAK-4 signaling in the setting of treatment with BTK inhibitors has been shown in B-cell lymphomas making IRAK-4 inhibition an attractive therapeutic target." (PMID 37954584, 2023). "The pharmaceutical therapy of B-cell lymphomas has changed significantly since the development of targeted drugs such as Bruton tyrosine kinase (BTK) inhibitors." (PMID 37894699, 2023). "It intends to serve as a reference for nurses and pharmacists involved in the care of patients with indolent B-cell NHL or CLL who are being treated with BTK inhibitors." (PMID 37185435, 2023). "BTK activity in B-cell differentiation, proliferation, and survival also applies to the microenvironment of B-cell lymphomas." (PMID 36986499, 2023). "In B-cell NHL, emavusertib has shown synergy with covalent BTK inhibitors such as ibrutinib and with PI3K pathway inhibitors such as idelalisib and copanlisib." (PMID 37954584, 2023). "It is a first‐generation BTK inhibitor that has shown excellent anti‐cancer activities in different subtypes of B‐cell lymphomas." (PMID 37929016, 2023). "Emerging evidence is demonstrating the therapeutic benefit of IRAK-4 inhibition in B-cell lymphomas, along with possibly reversing BTK inhibitor resistance." (PMID 37954584, 2023). "Persistent TLR signaling downstream of BTK and MYD88 in B-cell NHL patients treated with BTK inhibitors highlight the need to target other proteins in the TLR pathway." (PMID 37954584, 2023). "Collectively, these findings demonstrate the potency of TL-895 for BTK and its efficacy in models of B-cell lymphoma despite its refined selectivity." (PMID 37989777, 2023). "With its critical role in normal B-cell function and reported increased expression and activation in several B-cell NHLs, BTK has become an attractive drug target for these neoplasms." (PMID 37185435, 2023). "Herein, we identified that the third-generation EGFR inhibitor ASK120067 exhibited potency against B-cell lymphoma and T-cell leukemia by targeting BTK and ITK, respectively." (PMID 36588692, 2022). "Ibrutinib was originally used to cure B-cell lymphoma because of its effect as a Bruton’s tyrosine kinase (BTK) inhibitor." (PMID 36032118, 2022). "Ibrutinib (IB) is a specific inhibitor of the enzyme Bruton’s tyrosine kinase (BTK), used for treatment of B-cell lymphoma." (PMID 36146030, 2022). "Our research expands the clinical indications for ASK120067 and provides a new treatment option for B-cell lymphoma through targeting BTK." (PMID 36588692, 2022). "Constitutive activation of the B‐cell receptor (BCR) and signaling through Bruton's tyrosine kinase (BTK) has traditionally been considered mandatory in B‐cell lymphomas." (PMID 36051027, 2022). "Ibrutinib, acalabrutinib, and zanubrutinib are Bruton tyrosine kinase (BTK) inhibitors approved for certain indolent B cell non-Hodgkin's lymphoma (NHL)." (PMID 35096069, 2022). "BTK is centrally involved in BCR/NF-κB signaling pathway and BTK inhibitors (BTKis) were developed as promising novel agents of B-cell lymphoma." (PMID 36465385, 2022).